RET (ret proto-oncogene)
Diseases named in the same sentence as RET in open-access papers (continued):
Sharing a sentence is not in itself a finding about the gene and the disease.
lung cancer (299 papers, 2005 to 2026). A malignant neoplasm involving the lung. "Especially, mutations of RET are well known to be causative of malignant tumour development in the endocrine system and in lung cancer." (PMID 39610047, 2025). "In lung cancer, RET rearrangements have been associated with “cold” tumors and poor response to anti-PD1 therapies." (PMID 40756116, 2025). "There are selective RET inhibitors, selpercatinib and pralsetinib, that have been approved for the treatment of thyroid and lung cancers harboring RET mutations." (PMID 41562905, 2025). "RET gene (proto-oncogene tyrosine-protein kinase receptor RET) is a rare genetic mutation in lung cancer, with only 1-2% incidence." (PMID 39605888, 2024). "The median TMB in our RET-altered patients was significantly lower than that seen in other types of lung cancers, including those driven by other oncogenic mutations, which are typically found in non-smokers." (PMID 38317126, 2024). "We propose the consideration of this dual-target approach, specifically employing ensartinib and pralsetinib, in managing RET-rearranged lung cancer coexisting with targetable ALK mutations." (PMID 38698976, 2024). "Diseases associated with ADAM12 include lung cancer and ectopic gestation, and the related pathways include RET signal transduction and G-protein–coupled receptor signal transduction." (PMID 38575125, 2024). "Considering that RET mutation is rare in lung cancer cases, we performed whole exon sequencing on these three nodules to differentiate between multiple primary lung cancers and intrapulmonary metastatic cancer." (PMID 39605888, 2024). "It has demonstrated significant effectiveness in RET fusion-positive lung cancer and RET-mutated MTC, resulting in substantial tumor shrinkage and extended periods of progression-free survival for patients." (PMID 39272672, 2024). "The formation of tumors is primarily associated with RET gene fusions, which account for only 1-2% of lung cancers." (PMID 39605888, 2024). "Tyrosine kinase inhibitors with anti-RET activity are effective in treating patients with lung cancer caused by RET rearrangement." (PMID 36909198, 2023). "The most frequently found ESCAT I alteration was a PI3CKA mutation in breast cancer, followed by RET fusion alterations in lung cancer and MSI high for all cancers." (PMID 36923436, 2023). "The RET mutation (KIF5B–RET fusion), which is found in 1%–2% of lung cancer patients and is also targetable by multiple treatment modalities, was discovered in one patient by liquid biopsy but missed by tissue biopsy." (PMID 35785173, 2022). "Aberrant RET activity is associated with poor prognosis of thyroid and lung carcinoma patients, and is strongly correlated with increased risk of distant metastases." (PMID 35957881, 2022). "We identified seven different LP/P variants in three driver genes (EGFR, MET, and RET) in 0.03% of unselected lung cancer patients." (PMID 33898318, 2021). "Mutations and rearrangements in RET are most commonly observed in papillary thyroid carcinomas and in lung cancer." (PMID 32560187, 2020). "Multivariate analysis later confirmed that a positive RET fusion protein gene was an independent risk factor for brain metastasis in lung cancer patients (P = .003)." (PMID 31769228, 2020). "Confirmed responses to multikinase inhibitors with activity against RET, such as cabozantinib and vandetanib, can be achieved in some patients with lung cancer harboring RET-rearrangement or RET-mutation." (PMID 32411236, 2020). "Rearranged during transfection (RET) mutations/fusions represent one such target with drug development efforts focused on identifying agents that can be used to treat this subgroup of lung cancer patients." (PMID 31058838, 2019). "Like other oncogenic driver mutations in lung cancer, patients with RET fusions are typically associated with younger age, female gender, non-smokers and Asian ethnicity." (PMID 31058838, 2019).
lung cancer (continued). "Mucinous cribriform pattern was a previously reported histologic feature as a fusion gene-associated feature, such as ALK, ROS1, and RET rearranged lung cancer." (PMID 31561631, 2019). "GFL-independent RET activation, through rearrangement or point mutations occurs in thyroid and lung cancers." (PMID 30666215, 2018). "For instance, high levels of RET expression in ASCL1+ tumours were associated with significantly shorter OS in stage 1 lung cancer and other lung adenocarcinomas." (PMID 27092013, 2016). "Deregulated RET activity has been associated with the development, progression and/or resistance to therapy of certain thyroid, breast and lung cancer subtypes." (PMID 25409876, 2014). "RET fusion gene is a driver gene mutation found in 1%–2% of non‐small cell lung cancers." (PMID 41036187, 2025). "We showcase the benefit of the Onkopus match types using the sunburst rays for finding clinical evidence on RET:p.M918T, a pathogenic variant that may occur primarily in thyroid and lung cancer tissues." (PMID 40377094, 2025). "Interestingly, genetic testing for lung cancer-related driver genes revealed the presence of the rare RET mutation in all three nodules." (PMID 39605888, 2024). "This case underscores that a dual-target therapy involving ALK inhibitors, specifically ensartinib and pralsetinib, could be a viable approach in cases of RET-rearranged lung cancer with concurrent targetable ALK mutations." (PMID 38698976, 2024). "This might be due to the presence of mutations that were responsive to crizotinib, such as RET translocation, in responsive lung cancers." (PMID 35628598, 2022). "The oncoprotein is induced by RET gene and its fusion partner gene, which also causes the activation of associated signaling pathways, which can make cells malignant and progress toward lung cancer." (PMID 36582799, 2022). "In addition, in some patients with lung cancer M918T (MEN2B) RET mutation and fusion with other proteins was identified." (PMID 32993133, 2020). "Importantly, RET levels negatively correlate with lamin B1 levels in lung cancer patients, supporting a link between lamin B1 loss and RET upregulation." (PMID 31015297, 2019). "Oncogenic RET mutations and copy number amplification were also recently found in lung cancer." (PMID 31015297, 2019). "Importantly, the RET expression in the tumors negatively correlated with the lamin B1 expression, supporting a link between lamin B1 loss and RET upregulation in lung cancer patients." (PMID 31015297, 2019). "However, the mechanisms underlying acquired resistance to RET TKIs in lung cancer patients remain to be elucidated, and the molecular process by which cancer cells acquire such resistance needs to be investigated." (PMID 29434222, 2018). "Additionally, patients with EGFR-mutated lung cancer, positive for RET fusions at the time of progression on osimertinib, who received the combination of the third-generation TKI and the RET inhibitor selpercatinib, gained clinical benefit associated with a safety profile." (PMID 40243603, 2025). "The RET gene, located on the long arm of chromosome 10 (10q11.21), encodes a membrane tyrosine kinase receptor that plays a role in various cancers, including medullary thyroid carcinoma, papillary thyroid carcinoma, lung cancer, breast cancer, colorectal cancer, and so on." (PMID 37718634, 2023). "Lung cancers showed typical non-small cell lung cancer (NSCLC) driver alterations (KRAS G12D, RET fusions, PIK3CA mutations) and pervasive tumor suppressor loss, with no microsatellite instability (MSI)-high cases." (PMID 41717185, 2026). "This case underscores the importance of comprehensive molecular testing across multiple lesions to guide precision therapy and provides clinical insights into RET fusion-positive lung cancer treatment and post-resistance combination strategies." (PMID 41821900, 2026).
lung cancer (continued). "The next-generation sequencing (NGS) performed in this study was DNA-based, utilizing a panel covering 11 oncogenic driver genes recommended by the NCCN guidelines for lung cancer, which includes RET fusion detection." (PMID 40599544, 2025). "From the COSMIC database, RET alterations were noted in 4.06% (239/5882) in all lung cancer specimens." (PMID 40452844, 2025). "For other prevalent actionable mutation in lung cancer KRAS, PIK3CA, FGFR3, MET, NRAS, and RET demonstrated 100 % specificity with varied sensitivities around 50 %." (PMID 40503459, 2025). "For advanced or recurrent RET fusion gene‐positive non‐small cell lung cancer, selpercatinib is effective as a first‐line treatment." (PMID 41036187, 2025). "Tobacco is a major carcinogen linked to lung cancer, but other genetic triggers, particularly mutations in KRAS, EGFR, ALK, BRAF, RET, MET and ROS1, are also central to its development." (PMID 40556802, 2025). "RET G810S was shown to evolve in a patient-derived xenograft model using a lung cancer sample with CCDC6-RET in mice treated orally with selpercatinib." (PMID 39655713, 2025). "First, we included a cohort of patients with RET‐rearranged lung cancer, a rare but therapeutically targetable subtype." (PMID 40751559, 2025). "This case describes a patient with lung cancer progression, presenting cerebral, cerebellar, and bilateral internal auditory canal (IAC) metastasis at the third line of therapy, with a RET-fusion mutation identified after nodule re-biopsy." (PMID 40276420, 2025). "The LIBRETTO-001 trial assessed the RET inhibitor selpercatinib in patients with RET-fusion-positive tumors beyond thyroid and lung cancers." (PMID 41153346, 2025). "In advanced or recurrent RET fusion gene‐positive non‐small cell lung cancer, selpercatinib is approved as a first‐line treatment." (PMID 41036187, 2025). "A survey of the extant literature reveals that the majority of studies on RET 5′/3′ expression imbalance have focused on lung cancer or on isolated cases of rare tumors." (PMID 41373459, 2025). "For instance, NTRK fusions (across all cancer types) but also other kinase fusions (for example, ALK, ROS and RET for lung cancers), are now included in the NGTDC." (PMID 38200255, 2024). "Evidence of RET fusions in solid tumors has predominantly been documented in thyroid and lung cancers." (PMID 39085487, 2024). "The treatment of lung cancers harboring a RET fusion has evolved from traditional chemotherapy towards targeted therapy with selective RTK inhibitors and immunotherapy." (PMID 39372862, 2024). "At present, the treatment of lung cancers exhibiting RET alterations primarily concentrates on the development of targeted therapies." (PMID 39872362, 2024). "Currently, there are FDA-approved targeted therapies for lung cancers with mutations and genomic alterations in EGFR, ALK, ROS-1, NTRK, MET, RET, HER2, and BRAF." (PMID 39272844, 2024). "In support, a recent international study among pathologists from Germany, the UK, Japan and the USA reported considerable knowledge and skill gaps in RET testing for lung cancer and TC." (PMID 38001324, 2024). "The research included data from 232 lung cancer patients with RET fusions, gathered from real-world clinical settings." (PMID 38317126, 2024). "According to previous studies, KIAA1217 is a fusion partner of rearranged during transfection (RET) fusion gene, and its fusion to RET leads to oncogenic transformation in lung cancer." (PMID 38741142, 2024). "RET inhibitors, like selpercatinib and pralsetinib, for RET rearrangements in lung cancer showed high efficacy and clinical benefit." (PMID 39176355, 2024). "A study of 74 patients with RET-rearranged lung cancer receiving checkpoint inhibitor therapy showed that the majority of patients had low PD-L1 expression levels and poorer responses to immunotherapy." (PMID 39057153, 2024).
lung cancer (continued). "Traditional multitarget kinase inhibitors have treated RET fusion-positive lung cancers but show limited efficacy." (PMID 39372206, 2024). "Concomitantly with these main targeted therapies, there are others that have already been approved by the FDA for lung cancer treatment targeting KRAS (G12C mutation), MET (exon 14 skipping), NTRK, HER2, and RET fusion." (PMID 38793028, 2024). "Acquired KHDRBS1–NTRK3 fusion has been reported in patients with KIF5B–RET-fusion lung cancer after selpercatinib treatment, along with RET-altered cancers exhibiting NTRK and ALK fusions." (PMID 38791529, 2024). "The median TMB observed in lung cancers with RET alterations stood at 5.2 mut/mb, ranging from 0 to 17.5." (PMID 38317126, 2024). "Moving forward, it will be important to develop next-generation RET inhibitors and other treatment option such as combination strategies, to overcome resistance and improve their prognosis with RET fusion-positive lung cancer." (PMID 39372862, 2024). "This case provides further evidence for the existence of RET rearrangements in ALK-positive lung cancer and their potential treatment response to a combination of ALK inhibitors and pralsetinib." (PMID 38698976, 2024). "ALK and RET gene fusions are significant driver genes in lung adenocarcinoma, and targeted therapies have been approved for these alterations in lung cancer." (PMID 39583122, 2024). "Rearranged during transfection (RET) gene fusions occur in 0.7% to 2% in lung cancer and 1% to 2% in non-small cell lung cancer." (PMID 37478265, 2023). "For example, cabozantinib was studied in RET-rearranged lung cancers and showed an overall response rate (ORR) of 28% (95% CI: 12–49), with progression free survival (PFS) of 5.5 months (95% CI: 3.8–8.4)." (PMID 38201460, 2023). "The reported effectiveness of pralsetinib and other specific RET inhibitors such as cabozantinib or selpercatinib has been limited to only a few patient-derived lung cancer cell lines or PDX models." (PMID 38132167, 2023). "RET-rearranged NSCLC lung cancers are also known to exhibit less differentiated tumors compared to other molecular types of NSCLC." (PMID 38132167, 2023). "Although RET fusions are known to occur across cancer types, they are more frequently found in thyroid, and to a lesser degree, lung cancers." (PMID 37277734, 2023). "Prospective data will be generated by the first line AcceleRET and LIBRETTO-431 studies that randomize patients with RET fusion-positive lung cancers to selective RET inhibitor therapy or chemotherapy +/− immunotherapy." (PMID 37627175, 2023). "With Selpercatinib and Pralsetinib, two RET-inhibitors are now available for patients with RET-altered thyroid or lung cancer." (PMID 35796778, 2023). "Vepafestinib also inhibited the growth of multiple lung cancer patient-derived cell lines harboring RET fusions with different N-terminal partners (CCDC6, KIF5B, TRIM33) and a RETC634W-mutation-positive MTC cell line." (PMID 37743366, 2023). "Of note, baseline immunophenotype did not correlate with responses to ICI activity, and the median PFS was 3.4 months, consistent with RET fusion-positive lung cancers being immunologically cold tumors." (PMID 37627175, 2023). "Historically, FISH has been used to identify gene fusion detection in clinical practice, as in the identification of ALK, ROS1, and RET rearrangements in lung cancer." (PMID 37143440, 2023). "In non‐small cell lung cancer (NSCLC), RET fusion is a rare driver gene alteration associated with a poor prognosis." (PMID 37718634, 2023). "Pathologists face challenges when contributing to the diagnosis of RET-altered thyroid and lung cancers." (PMID 37277734, 2023). "In the ARROW trial (focused on cancers of the lung and thyroid), Pralsetinib administration resulted in radiographic tumor size reduction in 90% of patients, including tumors harboring RET fusions." (PMID 36918928, 2023).
lung cancer (continued). "RET fusion-positive lung carcinomas exhibit poorer differentiated tumors compared to those with ALK or EGFR alterations." (PMID 38132167, 2023). "The observation aligns with the finding that RET fusion-positive lung carcinomas displayed a higher prevalence of poorly differentiated tumors in comparison to those with ALK or EGFR alterations." (PMID 38132167, 2023). "The emergence of new lung cancer molecular subtypes of RET fusion type and ROS1 fusion type has brought new vitality to the establishment of a new molecular typing diagnosis and treatment model." (PMID 35433677, 2022). "The data from 12 countries and 29 centres shows that KIF5B-RET (62.4%) and CCDC6-5B (20.8%) were found in 173 lung cancer patients with a positive RET fusion profile." (PMID 36582799, 2022). "Multitarget inhibitors with anti-rearranged during RET action have been studied in patients with RET-rearranged lung cancer in several preclinical models, clinical trials, and retrospective investigations to date." (PMID 36499382, 2022). "In a phase 3 study of selpercatinib for RET-positive lung cancer, the efficacy of molecular-targeted drugs, in addition to the therapeutic effects of cytotoxic drugs will be clarified." (PMID 36452495, 2022). "RET fusions have been identified in 5–10% of papillary thyroid cancers and 1–2% of lung cancers and involve distinct fusion partners, including KIF5B in lung adenocarcinoma and CCDC6 in thyroid and lung cancer." (PMID 35510953, 2022). "This is particularly urgent in lung cancer, where mutations in EGFR, ALK, ROS, RET, METex14 skipping, BRAF, and KRAS should be identified before initial treatment." (PMID 35862868, 2022). "Although the ratio of resistant cases without RET resistance mutations is strikingly low, resistance is still a major challenge in RET fusion-positive lung cancer treated with RET TKIs." (PMID 36508072, 2022). "Recent studies indicate that amplification of MET is a druggable genetic mechanism of resistance in RET fusion–positive lung cancer." (PMID 35510953, 2022). "CCDC6-RET is the most common RET fusion in papillary thyroid cancer, which was also identified in lung cancer, acute lymphoblastic leukemia, and other cancers; detected here in breast fibrosarcoma." (PMID 36009413, 2022). "Since identification of the first RET fusion (KIF5B-RET) in lung cancer, significant efforts have been made to identify additional novel RET fusions in NSCLC." (PMID 35957881, 2022). "Although both drugs have been studied in adult thyroid and lung cancer patients, there are very few reports regarding the effectiveness of RET selective inhibitors in children." (PMID 36358717, 2022). "To date, a number of clinical studies have investigated a variety of multikinase inhibitors with anti-RET activity, such as vandetanib, cabozantinib and alectinib, in patients with RET-rearranged lung cancer." (PMID 36451418, 2022). "The TKIs selpercatinib and pralsetinib were approved by the FDA for the treatment of advanced RET fusion-positive lung cancer in 2020." (PMID 36508072, 2022). "And they found that stage IV RET fusion-positive lung cancer seems to have a higher brain metastasis rate of 25% (33/133)." (PMID 36582799, 2022). "On the other hand, while the frequency of NCOA4-RET was low (2.3%, 6/262) in lung cancer, it was the most frequent RET fusion (44%, 7/16) in colorectal cancer (Bonferroni’s post-test, P < 0.0001)." (PMID 36369474, 2022). "Several multiple kinase inhibitors (vandetanib, cabozantinib, RXDX-105, and levantinib) and RET-specific inhibitors (pralsetinib and selpercatinib) with modest inhibitory activity have been developed for the treatment of RET-positive lung cancer patients." (PMID 35268691, 2022). "Pralsetinib entered Phase I/II clinical trial in 2017 (NCT03037385) to assess safety and efficacy in patients with RET fusion-positive thyroid and lung cancers." (PMID 35957881, 2022).